U2 (U2 spliceosomal RNA )
Synonyms: LOC124904141
Gene: Small nuclear RNA gene on chromosome 17 (43,277,978 to 43,278,168, reverse strand). Ensembl gene ENSG00000274862.
Gene Ontology:
Molecular function: pre-mRNA branch point binding
Biological process: mRNA branch site recognition
Cellular component: U2 snRNP
Homologues: Orthologues: chimpanzee U2 (100% identical), macaque U2 (100% identical), dog U2 (99% identical), pig U2 (48% identical), rat LOC120094029 (36% identical). Paralogues in human: U2 (100% identical), RNU2-2 (96% identical), U2 (95% identical), RNU2-3P (93% identical), RNU2-4P (93% identical), RNU2-17P (90% identical), RNU2-6P (90% identical), RNU2-48P (89% identical), RNU2-52P (89% identical), RNU2-59P (89% identical), RNU2-25P (87% identical), RNU2-26P (87% identical), and 68 more.